RN7SKP178 (RN7SK pseudogene 178)
Gene: Miscellaneous RNA gene on chromosome 2 (205,900,630 to 205,900,958, forward strand). Ensembl gene ENSG00000201875.
Homologues: Orthologues: chimpanzee 7SK (99% identical). Paralogues in human: 7SK (85% identical), RN7SKP187 (82% identical), RN7SKP227 (80% identical), RN7SKP118 (80% identical), RN7SKP185 (79% identical), RN7SKP48 (79% identical), RN7SKP62 (78% identical), RN7SKP76 (77% identical), RN7SKP174 (76% identical), RN7SKP292 (75% identical), RN7SKP55 (75% identical), RN7SKP160 (72% identical), and 284 more.